FAM25G (family with sequence similarity 25 member G)
Synonyms: bA301J7.4
Tractability: No criterion of Open Targets' tractability assessment is met for any kind of drug.
Gene: Protein-coding gene on chromosome 10 (47,487,219 to 47,491,700, reverse strand). Ensembl gene ENSG00000189090.
Genetic constraint (gnomAD): Loss-of-function variants: 1 observed, 1.87 expected, observed/expected ratio (o/e) 0.54, 90% interval 0.18 to 1.77. That is too few expected variants to judge how well the gene tolerates losing a copy. Missense variants: 15 observed, 23.08 expected, observed/expected ratio (o/e) 0.65, 90% interval 0.43 to 1. Synonymous variants: 6 observed, 13.32 expected, observed/expected ratio (o/e) 0.45, 90% interval 0.25 to 0.89.
Homologues: Orthologues: mouse Fam25a (80% identical), rat Fam25a (80% identical), guinea pig Fam25a (78% identical), dog FAM25A (71% identical). Paralogues in human: FAM25A (100% identical), FAM25C (100% identical).
Diseases named in the same sentence as FAM25G in open-access papers:
FAM25G is named in the same sentence as 1 disease in open-access papers, as found by Europe PMC text mining. Sharing a sentence is not in itself a finding about the gene and the disease.
FAM25G shares sentences with these, for which no sentence is quoted: Esotropia (1 paper).